SCAP (SREBF chaperone)
Diseases named in the same sentence as SCAP in open-access papers (continued):
Sharing a sentence is not in itself a finding about the gene and the disease.
atherosclerosis (8 papers, 2008 to 2024). A disease characterized by the build-up of fatty material and calcium deposition in the arterial wall resulting in partial or complete occlusion of the arterial lumen. "We established a transgenic knock-in mouse model of atherosclerosis with an activating D443N mutation at the sterol-sensing domain of SCAP (SCAPD443N) by microinjection." (PMID 34094640, 2021). "In this study, we explored whether sterol-resistant SCAP (D443N mutation) in vascular smooth muscle cells (VSMCs) of mice promotes vascular inflammation and accelerates the occurrence and progression of atherosclerosis." (PMID 34094640, 2021). "From these evidences in all, we could make a reasonable inference that SCAP mutation would predispose to the pathogenesis of atherosclerosis." (PMID 29245966, 2017). "We conclude that SREBF-2 and SCAP may be implicated in the progression of atherosclerosis and the risk of developing SCD." (PMID 19116028, 2008). "In the present study, we generated a new mouse model of sterol-resistant SCAP (D443N mutation) in VSMCs crossed with the hyperlipidemic ApoE-/- mouse to elucidate the mechanisms linking cholesterol metabolism and inflammatory disorders in the development of atherosclerosis." (PMID 34094640, 2021). "Based on our data, we believe that an inflammatory pathway is an important mechanism by which sterol-resistant SCAP in VSMCs amplifies atherosclerosis." (PMID 34094640, 2021). "Our previous studies showed that VSMC-specific SCAP knockdown prevented the development of atherosclerosis in ApoE-/- mice by activating autophagy, with a decreased vascular inflammatory response." (PMID 34094640, 2021). "These in vivo data suggested that sterol-resistant SCAP overexpression in VSMCs promoted the development of atherosclerosis and contributed to plaque stability in ApoE-/- mice." (PMID 34094640, 2021). "Our study highlights the consequences of sterol-resistant SCAP overexpression in regulating local inflammation on vascular and endothelial cell function in atherosclerosis." (PMID 34094640, 2021). "Although these mutations indicated that increased SCAP signaling would promote hypercholesterolemia, the role of sterol-resistant SCAP in atherosclerosis has not been studied." (PMID 34094640, 2021). "Several studies showed that variations in SCAP gene might play a role in the lipid level and progression of atherosclerosis." (PMID 28542467, 2017). "As regulators of this cholesterol metabolism, SREBF-2 and SCAP might play a role in the progression of atherosclerosis." (PMID 19116028, 2008). "We have also discovered that crosstalk between SCAP/SREBP and the TLR4-MyD88-NF-κB inflammation pathway mediates foam cell formation in atherosclerosis." (PMID 39224584, 2024). "In this study, we created a new model of VSMCs specifically expressing sterol-resistant SCAP (D443N mutant) in both C57BL/6J and ApoE-/- mice to reveal the effects of SCAP on the NLRP3 inflammasome in VSMCs and the development of atherosclerosis." (PMID 34094640, 2021). "However, the underlying mechanism by which the cholesterol homeostatic regulator SCAP-SREBP2 mediates NLRP3 in?ammasome activation in vascular inflammation and atherosclerosis is unclear." (PMID 34094640, 2021). "Given the central role of the SREBF-SCAP pathway in the regulation of cholesterol, the variation in the SREBF-2 and SCAP locus might affect the progression of atherosclerosis." (PMID 19116028, 2008). "Moreover, SCAP overexpression promotes the translocation of SCAP and NLRP3 inflammasomes to the Golgi apparatus, increasing the activation of the NLRP3 inflammasome pathway and thereby expediting atherosclerosis." (PMID 39224584, 2024). "However, the dysregulation of the SCAP-SREBP pathway in the development of atherosclerosis is not fully clarified and is still being enthusiastically explored." (PMID 34094640, 2021).
diabetes (6 papers, 2013 to 2025). "Here we highlight the interaction between cholesterol disorders and pathological astrocytic responses, presenting SCAP as a potential target for therapeutic intervention in diabetes-associated cognitive impairment." (PMID 41016959, 2025). "In this model, diabetes mellitus reduces expression of SCAP in the brain, and this reduction of SCAP causes a defect in SREBP-2 processing, leading to a reduction in active SREBP-2." (PMID 23585733, 2013). "Research Hypothesis Illustration: SCAP and complement C3 play a role in cholesterol-driven astrocyte responses in diabetes-associated cognitive impairment." (PMID 41016959, 2025). "C57BL/6J wild-type and astrocyte-specific SCAP knockout mice were fed a high-fat diet and treated with streptozotocin to induce type 2 diabetes mellitus (T2DM)." (PMID 41016959, 2025). "TXNIP knockdown mitigated the accumulation of renal tubular lipids in diabetes through the regulation of SCAP, thereby inhibiting the SCAP-SREBP-2 signaling pathway, resulting in reduced cholesterol uptake and synthesis." (PMID 37144033, 2023). "A conditional knockout of SCAP in the mouse brain identifies impaired cholesterol synthesis as a potential link between diabetes and altered brain function." (PMID 23585733, 2013). "Brain-specific heterozygous SCAP knockout mice have reduced levels of cholesterol genes and exhibit a 30% reduction in brain cholesterol synthesis, mimicking what is observed in diabetes." (PMID 23585733, 2013). "Thus, diabetes results in a reduction of SCAP expression, which contributes to a reduction of brain cholesterol synthesis." (PMID 23585733, 2013).
steatosis (6 papers, 2021 to 2024). Increased lipid within the cytoplasm of cells. "For example, liver-specific PTEN deficiency results in excess lipids and steatosis in mice, whereas when combined with SCAP deletion it reduces steatosis, exacerbates the later-stage development of inflammation and liver injury, and accelerates the development of NASH and HCC." (PMID 38137501, 2023). "Our findings indicate that KLF2 promotes steatosis by upregulating SCAP expression and activating SREBP1 downstream targets that are involved in lipogenesis." (PMID 37949368, 2024). "Together, these results indicate that SCAP deletion inhibited hepatic lipogenesis and steatosis in PTENΔL mice, but unexpectedly induced severe liver injury and inflammation." (PMID 35380992, 2022).
viral infection (6 papers, 2014 to 2025). "Loss of SCAP also correlated with heightened resistance to viral infection in in vitro and in vivo models, confirming the functional equivalence between activation of type I interferon pathway and inhibition of lipid metabolism." (PMID 29915602, 2018). "Since IFN-β protects host cells against virus infection, we assessed whether SCAP could restrict HSV-1 infection." (PMID 26900919, 2016).
colon cancer (5 papers, 2018 to 2023). "BBR reduces lipogenesis and the spread of colon cancer cells by promoting PLZF-mediated SCAP ubiquitination." (PMID 36937842, 2023). "BER has previously been demonstrated to decrease lipid accumulation in porcine oocytes, colon cancer cells, and mouse liver tissue by suppressing the expression of genes that drive lipid buildup, such as SCAP, SREBP-1, PPARG, SCD1, and FASN." (PMID 37237857, 2023). "To further confirm the functional importance of de novo lipid biosynthesis in colon cancer, we silenced the expression of SCAP, a sterol-sensing SCAP, in DLD1 and Pt130 cells using lentivirus-mediated RNAi." (PMID 29449559, 2018). "Additionally, berberine inhibited colon cancer cell metastasis by suppressing lipogenesis via promoting promyelocytic leukaemia zinc finger (PLZF)-mediated SCAP ubiquitination." (PMID 35889396, 2022). "In addition, knockdown of SCAP inhibited cell proliferation in both colon cancer cell lines." (PMID 29449559, 2018). "Berberine could also modulate lipogenesis by targeting the SREBP cleavage-activating protein/sterol regulatory element-binding protein-1 (SCAP/SREBP-1) pathway, and then inhibiting colon cancer cell proliferation." (PMID 35889396, 2022).
glioblastoma (5 papers, 2020 to 2025). The most malignant astrocytic tumor (WHO grade IV). "This suggests that SCAP N-glycosylation is a critical factor for EGFRvIII-induced glioblastoma tumorigenesis." (PMID 40097417, 2025). "Fatostatin blocks SCAP–SREBP translocation from the endoplasmic reticulum to the Golgi apparatus in the models of glioblastoma, prostate, lung, and pancreatic cancers." (PMID 40427160, 2025). "Separately, miRNA-29 was identified as a regulator of the negative feedback mechanism that modulates SREBP-cleavage activating protein and sterol regulatory element-binding protein-1 (SCAP/SREBP-1) signaling in glioblastoma growth." (PMID 36013278, 2022). "Treatment of glioblastoma xenografts with miR-29 significantly suppressed tumor growth by inhibiting the SCAP/SREBP-1 and lipogenesis." (PMID 36013278, 2022). "Dissociation of SCAP induces adipogenesis and glioblastoma growth through activation of SREBP1." (PMID 36969840, 2023). "Interestingly, miR-29 inversely represses SCAP and SREBP1 expression and drives glioblastoma growth by interacting with the 3′-UTR of SCAP and SREBP1." (PMID 36969840, 2023). "In glioblastoma, SREBP1, regulated by SCAP N-glycosylation, is highly activated." (PMID 36969840, 2023). "Moreover, N-glycosylation of SREBP cleavage-activating protein (SCAP) is essential for Golgi localization and activation of SREBP once EGFR induced glucose uptake in glioblastoma multiforme (GBM)." (PMID 33511116, 2020). "In addition, miR-29 mediates a negative feedback loop regulating the SCAP/SREBP1 signaling pathway and lipogenesis in glioblastoma." (PMID 40427160, 2025).
Hypercholesterolemia (5 papers, 2020 to 2022). An increased concentration of cholesterol in the blood. "Since the SCAP/SREBP2 pathway is closely linked to cholesterol metabolism and hypercholesterolaemia, we further detected the signalling pathway." (PMID 35354475, 2022). "Therefore, inhibition of SCAP signaling seems to be an attractive strategy to treat hypercholesterolemia and metabolic diseases." (PMID 34094640, 2021). "Therefore, this review will discuss the various roles of SCAP in lipogenesis and the inflammatory response as well as newly discovered antagonists of SCAP as putative therapeutic targets for hypertriglyceridemia and hypercholesterolemia." (PMID 32385422, 2020).
type 2 diabetes (5 papers, 2013 to 2025). "There is also a significant, but smaller, reduction of SCAP protein in the cerebral cortices of db/db mice (a model of type 2 diabetes), consistent with a modest down-regulation of genes of the cholesterol synthesis pathway in the brains of these animals." (PMID 23585733, 2013). "We now show that in mouse models of type 1 and type 2 diabetes, this is, in part, the result of a decrease of SCAP." (PMID 23585733, 2013). "This study aimed to investigate whether or not SCAP-mediated intracellular cholesterol feedback is disturbed in the kidneys of rats with type 2 diabetes induced by high-fat/sucrose diet and low-dose streptozocin (STZ)." (PMID 24369464, 2013).
COVID-19 (4 papers, 2022 to 2023). A disease caused by infection with severe acute respiratory syndrome coronavirus 2. "CCRL2, LZTFL1, SCAP, and SACM1L are also differentially expressed in at least one experiment that measures differential expression of genes in lung tissues and related cell lines infected with COVID-19 or other viruses that stimulate similar immune responses." (PMID 36763080, 2023).
lipid metabolism disorders (4 papers, 2015 to 2022). "Rather, stimuli-induced SCAP expression appeared to rely on BRG1 suggesting that BRG1 is a pathogenic factor-driven regulator of lipid metabolism disorders." (PMID 33718362, 2021). "It is thought that TMP can alleviate lipid metabolism disorders through downregulating PAQR3 and inhibiting SCAP/SREBP-1c signaling pathways." (PMID 35500001, 2022). "In addition, TMP can inhibit the progress of As and ameliorate lipid metabolism disorder by downregulating PAQR3 and inhibiting SCAP/SREBP-1c signaling pathway in these mice." (PMID 28491104, 2017). "In conclusion, we showed that TMP could inhibit the progress of As and ameliorate lipid metabolism disorder by downregulating PAQR3 and inhibiting SCAP/SREBP-1c signaling pathway in ApoE−/− mice fed with a high-fat diet." (PMID 28491104, 2017). "Thus, TMP may ameliorate lipid metabolism disorder and As by downregulating PAQR3 and inhibiting SCAP/SREBP-1c signaling pathway." (PMID 28491104, 2017).
breast carcinoma (3 papers, 2018 to 2024). "One of these genes is insulin-induced gene 1 protein (INSIG1), which is regulated by insulin and plays a role in blocking cholesterol biosynthesis by interacting with the SCAP-SREBP complex was found to be correlated with breast cancer cell viability." (PMID 38812058, 2024). "These genes included BPTF, PHF5A, and SPG7 in cancer of female genital organs, as well as FGF10, NFIX, and SCAP in breast cancer." (PMID 38409266, 2024). "Previous studies have shown that FS affects not only SCAP/SREBP activity but also protein translocation from the endoplasmic reticulum to the Golgi23, so we asked whether FS might cause EnRS in breast cancer cells." (PMID 30140005, 2018).
HCMV infection (3 papers, 2013 to 2024). "Furthermore, shRNA-mediated targeting of SCAP, a protein important for SREBF1 processing and activation, has been shown to attenuate HCMV infection." (PMID 38117060, 2024).
Hyperinsulinemia (3 papers, 2015 to 2025). An increased concentration of insulin in the blood. "Very recently, we also documented that the AGEs accumulation, the co-localisation between AGEs and SCAP-(hyper)expressing cells (suggestive for SCAP glycosylation) and hyperinsulinemia combine to cause SREBP1c activation in muscle fibers." (PMID 29342166, 2018). "Pathophysiological analyses link hyperinsulinemia and chronic inflammation to impaired SCAP/SREBP2 regulatory control, driving pathological cholesterol accumulation in murine models." (PMID 40247356, 2025).
lung carcinoma (3 papers, 2022). "To understand the biological significance of SCAP in the development and progression of lung cancer, especially in patients with NSCLC, we evaluated the levels of SCAP and its ligand SREBP-1 in lung cancer specimens (n = 98) through IHC staining." (PMID 35806291, 2022). "The present study demonstrated that SREBP-1 and SCAP levels were positively correlated with disease progression and a poor prognosis in lung cancer." (PMID 35806291, 2022). "The circRNA hsa_circ_0065214 derived from its host gene SCAP (collectively circSCAP) was markedly downregulated in lung cancer." (PMID 35365208, 2022). "CircSCAP is derived from exons 3–5 of the SREBF chaperone (SCAP) gene, and is significantly downregulated in lung cancer tissues and negatively associated with poor prognosis." (PMID 36142352, 2022). "Finally, we developed therapeutic strategies involving the inhibition of SREBP-1 and SCAP signaling and the induction of hsa-miR-497 expression to inhibit lung cancer chemoresistance and progression." (PMID 35806291, 2022). "Our results may serve as a reference for the design of future clinical trials of therapeutic modalities that target the SREBP-1/hsa-miR-497-5p/SCAP/FASN oncometabolic signaling axis to overcome chemoresistance in patients with lung cancer." (PMID 35806291, 2022). "In addition, the present study provides a foundation for the design of future clinical trials evaluating the efficacy of targeting SREBP-1/hsa-miR-497-5p SCAP/FASN signaling for the treatment of chemoresistant lung cancer." (PMID 35806291, 2022).
Hepatic fibrosis (2 papers, 2020 to 2022). The presence of excessive fibrous connective tissue in the liver. "The activity of the SCAP/SREBP/LPCAT3 axis was found to be inversely associated with liver fibrosis severity in human NASH." (PMID 35380992, 2022). "Simultaneously, injection of DPSCs and SCAP-Ss significantly reduced inflammatory infiltration, enhanced liver-associated gene expression, and finally relieved symptoms of hepatic fibrosis." (PMID 32399047, 2020). "Deletion of SCAP in PTENΔL mice induces severe liver fibrosis and accelerates liver cancer development." (PMID 35380992, 2022). "What is more, the therapeutic effect of SCAP-Ss and DPSCs on hepatic fibrosis in mice was investigated for the first time." (PMID 32399047, 2020). "In conclusion, SCAP-Ss possess preferable characteristics and efficacy on hepatic fibrosis in mice." (PMID 32399047, 2020). "Compared with the control group (CCl4), intravenous injection of SCAP-Ss significantly alleviated the pathological status of hepatic fibrosis by ameliorating the inflammatory infiltration, indicators of liver function (ALT, AST), and liver reconstruction-associated genes (Ck-18, Ck-19, and Hgf)." (PMID 32399047, 2020). "Dramatically, the SCAP-Ss exhibited indiscriminate efficacy on hepatic fibrosis in mice." (PMID 32399047, 2020).
hyperlipidemia (2 papers, 2020 to 2021). "Furthermore, we discuss recent studies regarding SCAP as a possible therapeutic target for hypertriglyceridemia and hyperlipidemia." (PMID 32385422, 2020).
Hypertension (2 papers, 2008 to 2017). The presence of chronic increased pressure in the systemic arterial system. "Only SCAP 2386A>G GG carriers had a higher prevalence of hypertension than subjects with other genotypes." (PMID 19116028, 2008). "A case-control study on 702 high blood pressure (HBP) children and 1319 controls was conducted to explore the correlation between single nucleotide polymorphism markers (rs12487736 and rs12490383) of SCAP and BP phenotypes." (PMID 28542467, 2017).
leukemia (2 papers, 2021 to 2025). A malignant (clonal) hematologic disorder, involving hematopoietic stem cells and characterized by the presence of primitive or atypical myeloid or lymphoid cells in the bone marrow and the blood. "SCAP was also identified as an Rpl22-regulated gene upon which leukemia survival depends." (PMID 41389200, 2025). "However, SCAP and SCD2, both targets of SREBP-1 and critical regulators of TG synthesis, were induced in Rpl22−/− leukemias, suggesting that SREBP-1 activation is also responsible for the augmented production of TG in Rpl22-deficient leukemias." (PMID 41389200, 2025).
liver cancer (2 papers, 2019 to 2022). An epithelial or non-epithelial malignant neoplasm that arises from the liver. "Taken together, these results indicate that RA-XII suppresses the liver cancer growth by inhibition of lipogenesis via SCAP-dependent SREBP suppression." (PMID 31083642, 2019).
microcephaly (2 papers, 2017 to 2023). A congenital or acquired developmental disorder in which the circumference of the head is smaller than normal for the person's age and sex. "Brains contain the highest levels of cholesterol in the body, and SCAP deletion in astrocytes showed microcephaly, without effects on astrocyte survival." (PMID 37024487, 2023).